BMPR2 (bone morphogenetic protein receptor type 2)
Description:
On ligand binding, forms a receptor complex consisting of two type II and two type I transmembrane serine/threonine kinases. Type II receptors phosphorylate and activate type I receptors which autophosphorylate, then bind and activate SMAD transcriptional regulators. Can also mediate signaling through the activation of the p38MAPK cascade. Binds to BMP7, BMP2 and, less efficiently, BMP4. Binding is weak but enhanced by the presence of type I receptors for BMPs. Mediates induction of adipogenesis by GDF6. Promotes signaling also by binding to activin A/INHBA.
Synonyms: BMPR-II; PPH1; BRK-3; T-ALK; BMPR3; BMR2; POVD1
Tractability: Small molecule: a structure with a bound ligand is known; a high-quality ligand is known; it has a binding pocket of medium quality; it belongs to a druggable protein family. Antibody: UniProt places it where antibodies can reach, with high confidence; its Gene Ontology location is reachable by antibodies, with high confidence; UniProt predicts a signal peptide or a membrane-spanning region; the Human Protein Atlas places it where antibodies can reach. PROTAC: ubiquitination databases record sites on it; its protein half-life has been measured; a small molecule that binds it is known. Other modalities: an approved drug acts on it.
Target class: Kinase; TKL protein kinase STKR family; Protein Kinase; Enzyme; TKL protein kinase group; TKL protein kinase STKR Type 2 subfamily
Chemical probes: CDD-1653
Gene: Protein-coding gene on chromosome 2 (202,376,327 to 202,567,751, forward strand). Ensembl gene ENSG00000204217.
Subcellular location: Cell membrane
Subcellular location (Human Protein Atlas): Nucleoplasm; Plasma membrane
Pathways (Reactome):
Signal Transduction: Signaling by BMP
Gene Ontology:
Molecular function: activin receptor activity, type II; BMP binding; cadherin binding; protein binding; protein tyrosine kinase binding; BMP receptor activity; transforming growth factor beta receptor activity; ATP binding; protein kinase activity; protein serine/threonine kinase activity; transmembrane receptor protein serine/threonine kinase activity
Biological process: BMP signaling pathway; cell differentiation; cell surface receptor protein serine/threonine kinase signaling pathway; cellular response to BMP stimulus; cellular response to starvation; chondrocyte development; endothelial cell apoptotic process; endothelial cell proliferation; lung vasculature development; negative regulation of cell growth; negative regulation of chondrocyte proliferation; negative regulation of smooth muscle cell proliferation; negative regulation of systemic arterial blood pressure; osteoblast differentiation; positive regulation of bone mineralization; positive regulation of epithelial cell migration; positive regulation of gene expression; positive regulation of osteoblast differentiation; positive regulation of SMAD protein signal transduction; positive regulation of transcription by RNA polymerase II; regulation of cell population proliferation; regulation of lung blood pressure; anterior/posterior pattern specification; aortic valve development; artery development; and 38 more
Cellular component: adherens junction; caveola; extracellular region; plasma membrane; receptor complex; axon; cell body; cell junction; cell surface; clathrin-coated pit; dendrite; membrane; postsynaptic density
Genetic constraint (gnomAD): Loss-of-function variants: 28 observed, 102.23 expected, observed/expected ratio (o/e) 0.27, 90% interval 0.2 to 0.38. The synonymous counts are far from expectation, so gnomAD's model fits this gene poorly and the ratio says little. Missense variants: 1,007 observed, 1,335.4 expected, observed/expected ratio (o/e) 0.75, 90% interval 0.71 to 0.79. Synonymous variants: 380 observed, 468.36 expected, observed/expected ratio (o/e) 0.81, 90% interval 0.75 to 0.88.
Gene-disease validity (ClinGen):
ClinGen rates the evidence that BMPR2 causes each of these diseases.
pulmonary arterial hypertension (autosomal dominant): Definitive. Pulmonary arterial hypertension (PAH) is a group of diseases characterized by mean pulmonary artery pressure >20 mmHg and elevated pulmonary arterial resistance leading to right heart failure.
congenital heart disease (autosomal dominant): Limited. A heart disease that is present at birth.
Homologues: Orthologues: macaque BMPR2 (99% identical), dog BMPR2 (97% identical), mouse Bmpr2 (97% identical), rabbit BMPR2 (96% identical), pig BMPR2 (96% identical), rat Bmpr2 (96% identical), guinea pig BMPR2 (93% identical), chimpanzee BMPR2 (80% identical), tropical clawed frog bmpr2 (77% identical), zebrafish bmpr2b (70% identical), zebrafish bmpr2a (50% identical). Paralogues in human: AMHR2 (18% identical), ACVR2A (17% identical), ACVR2B (17% identical), TGFBR2 (16% identical), ACVR1 (14% identical), ACVRL1 (14% identical), BMPR1B (13% identical), ACVR1B (13% identical), ACVR1C (13% identical), TGFBR1 (13% identical), BMPR1A (13% identical).
Diseases named in the same sentence as BMPR2 in open-access papers:
BMPR2 is named in the same sentence as 187 diseases in open-access papers, as found by Europe PMC text mining. Sharing a sentence is not in itself a finding about the gene and the disease. The quoted sentences say what the papers report.
pulmonary arterial hypertension (260 papers, 2006 to 2026). "Canonical pulmonary arterial hypertension genes such as BMPR2, KCNK3, and TBX4 are well described, but novel associations continue to emerge." (PMID 41133550, 2025). "Mutations in the BMPR2 signaling pathway are associated with the development of pulmonary arterial hypertension." (PMID 40720495, 2025). "In hereditary pulmonary arterial hypertension, BMPR2 mutations induce RV lipotoxicity, manifesting as FAO defects, triglyceride and ceramide deposition, leading to impaired RV hypertrophy and heart failure." (PMID 41463335, 2025). "The StratosPHere 2 trial will evaluate the efficacy of hydroxychloroquine and phenylbutyrate in pulmonary arterial hypertension caused by mutations in BMPR2 by focussing on the novel biomarker and other endpoints including safety." (PMID 40646581, 2025). "A previous study reported that chloroquine has been shown to enhance BMPR2 levels on the cell surface, whereas increased autophagic flux is associated with reduced BMPR2 levels in patients with pulmonary arterial hypertension (PAH)." (PMID 41116059, 2025). "Mutations in BMPR2, for example, have been shown to cause asthma-like symptoms and pulmonary hypertension in response to mild antigens in the airway." (PMID 40504147, 2025). "Pathologic variants in the bone morphogenetic protein receptor-2 (BMPR2) gene cause a pulmonary arterial hypertension phenotype in an autosomal-dominant pattern with incomplete penetrance." (PMID 38561801, 2024). "Experimental studies revealed a crosstalk between IL-6 and the bone morphogenetic protein BMP/SMAD pathway, and mutations of BMPR2 were associated with pulmonary hypertension and iron deficiency." (PMID 38999801, 2024). "For instance, APOLD1 and KCNA5, which are associated with pulmonary hypertension, showed similar expression patterns to BMPR2 in lung, artery and heart." (PMID 38730227, 2024). "This three-armed phase II precision medicine study will investigate BMPR2 target engagement and explore the efficacy of two repurposed therapies in pulmonary arterial hypertension patients with BMPR2 mutations." (PMID 39407331, 2024). "Germ-line mutations in the bone morphogenetic protein type II receptor (BMPR2; BMPR-II) gene cause the majority of cases of heritable pulmonary arterial hypertension (PAH)." (PMID 38673717, 2024). "This is the first report of different straight back characteristics in heritable pulmonary arterial hypertension with a novel germline BMPR2 variant." (PMID 38561801, 2024). "Decreased function of the BMPR2 gene is associated with a high risk of developing pulmonary hypertension." (PMID 37569308, 2023). "Bone morphogenetic protein receptor type 2 (BMPR2) variants have been associated with pulmonary arterial hypertension (PAH)." (PMID 36675162, 2023). "In humans, variation in the BMPR2 gene is the major cause of pulmonary arterial hypertension (PAH, OMIM #178600) and pulmonary venoocclusive disease 1 (OMIM #265450); however, no variation has been identified in individuals with oligodontia." (PMID 36675162, 2023). "Pathogenic mutations in the BMP receptor 2 (BMPR2) can cause one of the most severe types of pulmonary hypertension." (PMID 37237303, 2023). "Factors modulating the expression of BMPR2 are of particular importance because it is the most dominant genetic mutation that is linked directly to patients of pulmonary hypertension." (PMID 38001814, 2023). "Pulmonary arterial hypertension (PAH) can be caused by pathogenic variants in the gene bone morphogenetic protein receptor 2 (BMPR2)." (PMID 35627145, 2022).
pulmonary arterial hypertension (continued). "Bone morphogenetic proteins are thought to affect the vascular endothelium and smooth muscle, interfering with transforming growth factor beta signaling; therefore, mutation in BMPR2 is a cause of pulmonary hypertension." (PMID 35714115, 2022). "Monoallelic mutations in the gene encoding bone morphogenetic protein receptor 2 (Bmpr2) are the main genetic risk factors for heritable pulmonary arterial hypertension (PAH) with incomplete penetrance." (PMID 35269691, 2022). "BMPR2 mutation is a key risk factor for hereditary pulmonary arterial hypertension (hPAH), and about 20% of carriers will get the disease." (PMID 35370672, 2022). "For example, cells isolated from patients with heritable pulmonary arterial hypertension (HPAH) show mutations in the type 2 bone morphogenetic protein receptor (BMPR2) or Smad9." (PMID 35892126, 2022). "According to the pulmonary hypertension gene curation expert panel of pulmonary hypertension of ClinGen, the association of BMPR2, KCNK3, KDR, SMAD9, and TBX4 and PH is definitive, GDF2 is strong, and AQP1 has a limited disease relationship." (PMID 35627312, 2022). "Heterozygous mutations in BMPR2 (bone morphogenetic protein (BMP) receptor type II) cause pulmonary arterial hypertension." (PMID 35504921, 2022). "Upregulation of miR-19a has been associated with reducing the levels of the bone morphogenetic protein receptor type II (BMPR2) linked to pulmonary arterial hypertension." (PMID 36071532, 2022). "More exosomes can be isolated from growing endothelial cells of BMPR2 mutation carriers than from non-BMPR2 mutation carriers, which contain more translation-modulating tumor proteins involved in pulmonary hypertension." (PMID 36419957, 2022). "Heritable pulmonary arterial hypertension is associated with several gene mutations, with 75% having a mutation in the bone morphogenetic protein receptor 2 (BMPR2)." (PMID 35232468, 2022). "This study sought to validate 18FLT‐PET in an expanded cohort of pulmonary arterial hypertension patients in comparison to matched healthy controls and unaffected bone morphogenetic protein receptor type 2 mutation carriers." (PMID 34276963, 2021). "The interaction with genetic mutations on autosomal genes that cause heritable pulmonary arterial hypertension such as bone morphogenetic protein 2 (BMPR2) are examined." (PMID 34068984, 2021). "Mutations of BMPR2 in humans and mice also cause cardiovascular phenotypes that are associated with pulmonary arterial hypertension." (PMID 34488850, 2021). "It is already known that patients with genetic mutations in BMPR2 are more prone to pulmonary hypertension, and it has been suggested that this is because endothelial cells in these patients become more sensitive to TGFbeta." (PMID 34061599, 2021). "A genetic mutation in the bone morphogenetic protein 2 (BMPR2) gene has been linked to pulmonary arterial hypertension." (PMID 33663433, 2021). "Formation of this dimer is essential for ligand-induced receptor signaling and is targeted by mutations in BMPR2 in patients with pulmonary arterial hypertension (PAH)." (PMID 34400635, 2021). "Mutations in BMPR2 are found in 55–70% of severe pulmonary arterial hypertension (HPH) patients and 11−40% of idiopathic pulmonary arterial hypertension (IPH) cases." (PMID 34793329, 2021). "Monoallelic loss-of-function mutations in the gene encoding bone morphogenetic protein receptor 2 (BMPR2) are the main genetic risk factor for heritable pulmonary arterial hypertension." (PMID 33672218, 2021). "The best-known cause of hereditary pulmonary hypertension is a mutation in the bone morphogenetic protein receptor type 2 (BMPR2) gene, which belongs to the TGF-β superfamily." (PMID 32566097, 2020). "Germ-line mutations in ALK1 underlie hereditary hemorrhagic telangiectasia type 2 and BMPR2 mutations underlie pulmonary arterial hypertension (PAH)." (PMID 32576665, 2020).
pulmonary arterial hypertension (continued). "In view of the hereditary pulmonary arterial hypertension in this patient, the mutation of BMPR2 gene was considered." (PMID 32756122, 2020). "Hereditary factors play a role in the development of pulmonary hypertension, including a heterozygous mutation in the gene Bone Morphogenetic Protein Receptor Type 2 (BMPR2), found in 50–70% of patients with familial pulmonary hypertension." (PMID 32708482, 2020). "It is estimated that about 15-20% of patients with the BMPR2 gene mutation will develop pulmonary hypertension." (PMID 32566097, 2020). "Regarding the potential pathogenicity, it has been known that mutations leading to loss of function in BMPR2 would cause Primary Pulmonary Hypertension 1 and/or Pulmonary Venooclusive Disease 1 (OMIM: #600799)." (PMID 31475041, 2019). "The first report of a mutation in EIF2AK4 reponsible for hereditary pulmonary arterial hypertension came as a combined heterozygous mutation in conjunction with a BMPR2 mutation." (PMID 31711431, 2019). "In male hypoxic mice, hypoxia elevates 16αOHE1, which has been shown to synergise with BMPR2 deficiency and uncover a pulmonary hypertension phenotype in BMPR2-deficient transgenic mice." (PMID 30923189, 2019). "A recent study reported that selective enhancement of endothelial BMPR2 signaling by BMP9 was able to rescue endothelial cells from apoptosis and pulmonary arterial hypertension in mice carrying a heterozygous BMPR2 mutation." (PMID 30272025, 2018). "In contrast, growth factors associated with monocytic expansion, such as GM-CSF, increase inflammatory cell recruitment to the lungs in mice with the BMPR2 mutation, exacerbating pulmonary hypertension." (PMID 30081463, 2018). "Loss-of-function mutations in the BMPR2 gene cause severe vascular diseases, such as pulmonary arterial hypertension and, in rare cases, hereditary hemorrhagic telangiectasia." (PMID 30272025, 2018). "Patient AII.3 with the BMPR2 p.Q6* mutation was followed at an early stage after being diagnosed with ventricular septal defect and pulmonary hypertension." (PMID 29843651, 2018). "Endothelial dysfunction is a known consequence of bone morphogenetic protein type II receptor (BMPR2) mutations seen in pulmonary arterial hypertension (PAH)." (PMID 30158434, 2018). "As BMPR2 deficiency is associated with pulmonary arterial hypertension and more recently with atherosclerosis, we investigated the role of the BMP Type II receptors in mediating the expression of adhesion molecules." (PMID 28646109, 2017). "Genetic studies have shown that inactivating BMPR2 mutations occur in the majority of patients with familial pulmonary hypertension and up to 25% of patients with idiopathic pulmonary hypertension." (PMID 28859128, 2017). "While we see a decrease in miR129-5p levels with worsening HF symptoms, this should result in disinhibition of BMPR2 expression contrary to what occurs with inactivating mutations leading to idiopathic pulmonary hypertension." (PMID 28859128, 2017). "This identified an evolutionarily conserved sequence in the 3’ UTR of the gene encoding bone morphogenetic protein receptor 2 (BMPR2), a serine/threonine receptor kinase for which inactivating mutations have been linked to pulmonary hypertension." (PMID 28859128, 2017). "Mutations in the BMPR2 gene resulted in the development of familial primary pulmonary hypertension, but the role BMPR2 mutations play in the development of PH has not been clarified." (PMID 26539466, 2015). "Mutations in BMPR2 result in pulmonary Hypertension (PAH), a vascular disorder characterized by uncontrolled remodeling of the pulmonary arteries due to increased proliferation of VSMCs." (PMID 25763012, 2015). "One patient with signs of HHT and pulmonary arterial hypertension was found to have a non-sense mutation in the bone morphogenetic protein receptor, type II gene, BMPR2." (PMID 25674101, 2015).